UBE2D2 (ubiquitin conjugating enzyme E2 D2)
Description:
Accepts ubiquitin from the E1 complex and catalyzes its covalent attachment to other proteins. Catalyzes 'Lys-48'-linked polyubiquitination. Mediates the selective degradation of short-lived and abnormal proteins. Mediates ubiquitination of PEX5 and SQSTM1 and autoubiquitination of STUB1 and TRAF6. Essential for viral activation of IRF3.
Synonyms: PUBC1; UBC4; UBCH4; UBCH5B; E2(17)KB2; UBC4/5
Tractability: Antibody: the Human Protein Atlas places it where antibodies can reach. PROTAC: ubiquitination databases record sites on it; its protein half-life has been measured.
Target class: Enzyme; Transferase
Gene: Protein-coding gene on chromosome 5 (139,526,431 to 139,628,434, forward strand). Ensembl gene ENSG00000131508.
Subcellular location (Human Protein Atlas): Cytosol; Plasma membrane
Pathways (Reactome):
Immune System: Antigen processing: Ubiquitination & Proteasome degradation; CLEC7A (Dectin-1) signaling; Downstream TCR signaling; FCERI mediated NF-kB activation; IKK complex recruitment mediated by RIP1; Inactivation of CSF3 (G-CSF) signaling; Negative regulators of DDX58/IFIH1 signaling; TICAM1, RIP1-mediated IKK complex recruitment
Metabolism of proteins: E3 ubiquitin ligases ubiquitinate target proteins; Neddylation; Ribosome Quality Control (RQC) complex extracts and degrades nascent peptide; Synthesis of active ubiquitin: roles of E1 and E2 enzymes; ZNF598 and the Ribosome-associated Quality Trigger (RQT) complex dissociate a ribosome stalled on a no-go mRNA
Autophagy: PINK1-PRKN Mediated Mitophagy
Cellular responses to stimuli: Oxygen-dependent proline hydroxylation of Hypoxia-inducible Factor Alpha
Disease: Enterobacterial factors antagonize host defense
Protein localization: Peroxisomal protein import
Signal Transduction: Regulation of TNFR1 signaling
Gene Ontology:
Molecular function: protein binding; ubiquitin conjugating enzyme activity; ubiquitin protein ligase activity; ubiquitin-protein transferase activity
Biological process: protein autoubiquitination; protein K48-linked ubiquitination; protein polyubiquitination; protein ubiquitination; protein modification process; ubiquitin-dependent protein catabolic process
Cellular component: extracellular exosome; protein-containing complex; cytosol; nucleoplasm
Genetic constraint (gnomAD): Loss-of-function variants: 1 observed, 20.15 expected, observed/expected ratio (o/e) 0.0496, 90% interval 0.017 to 0.23. The upper end of that interval is the gene's LOEUF score, 0.23, which puts it in group 1 of 6, group 1 being the genes least tolerant of losing a copy. Missense variants: 35 observed, 163 expected, observed/expected ratio (o/e) 0.21, 90% interval 0.16 to 0.28. Synonymous variants: 54 observed, 51.88 expected, observed/expected ratio (o/e) 1.04, 90% interval 0.83 to 1.31.
Homologues: Orthologues: chimpanzee UBE2D2 (100% identical), guinea pig UBE2D2 (100% identical), mouse Ube2d2a (100% identical), rat Ube2d2 (100% identical), dog UBE2D2 (98% identical), pig UBE2D2 (95% identical), macaque UBE2D2 (83% identical). Paralogues in human: UBE2D3 (97% identical), UBE2D4 (93% identical), UBE2D1 (87% identical), UBE2E3 (65% identical), UBE2E1 (65% identical), UBE2E2 (65% identical), UBE2L5 (39% identical), UBE2L3 (38% identical), UBE2L6 (38% identical), UBE2Q2 (32% identical), UBE2Q1 (31% identical), UBE2QL1 (26% identical).
Diseases named in the same sentence as UBE2D2 in open-access papers:
UBE2D2 is named in the same sentence as 23 diseases in open-access papers, as found by Europe PMC text mining. Sharing a sentence is not in itself a finding about the gene and the disease. The quoted sentences say what the papers report.
breast cancer (9 papers, 2020 to 2024). A primary or metastatic malignant neoplasm involving the breast. "Studies indicate that in vitro transduction of circ‐UBE2D2 via exosomes can enhance resistance to tamoxifen in breast cancer, with recent findings showing circ‐UBE2D2 expression being 20‐fold higher in MCF‐7/TAM‐R‐Exo compared with MCF‐7/Par‐Exo." (PMID 39239069, 2024). "Circ_UBE2D2, an exosomal circular RNA that can sponge different microRNAs, is overexpressed in resistant breast cancer tissues and cell lines." (PMID 36132137, 2022). "Ubiquitin conjugating enzyme E2 D2 (UBE2D2) plays an important role in the development of breast cancer." (PMID 34445498, 2021). "Circ_UBE2D2 is upregulated in tamoxifen-resistant breast cancer, and circ_UBE2D2 could induce breast cancer tamoxifen resistance by regulating miR-200a-3p." (PMID 38186573, 2023). "They indicated that circ-UBE2D2 could promote breast cancer progression via acting as a sponge for two miRNAs, miR-1236 and miR-1287." (PMID 34400888, 2021). "In ER-positive breast cancer cells with tumor-associated macrophages (TAM), circRNA UBE2D2 (circ-UBE2D2) is upregulated, and TAM-resistant cells can release exosomes containing circRNA UBE2D2 to induce drug-sensitive BC cells to develop TAM resistance." (PMID 39713143, 2024). "Studies have clarified that circ-UBE2D2 is elevated in BC cell lines and tissues, predicts the poor prognosis, and strengthens Nolvadex resistance in breast cancer (BC)." (PMID 35196197, 2022). "Here, we assessed the expressions of six circRNAs that have been reported to be abnormally expressed in breast cancer: circ_0108942, circ_0001785, circ-ERBB2, circ-BMPR2, circ-UBE2D2, circ-IRAK3." (PMID 34732216, 2021).
acute kidney injury (2 papers, 2022 to 2025). Sudden and sustained deterioration of the kidney function characterized by decreased glomerular filtration rate, increased serum creatinine or oliguria. "Circ_UBE2D2 has been found to target binding sites for multiple miRNAs associated with septic acute kidney injury, impacting disease progression." (PMID 38779731, 2025).
colorectal cancer (2 papers, 2011 to 2020). A primary or metastatic malignant neoplasm that affects the colon or rectum. "These genes included heat shock 70kDa protein 4 (HSPA4), ubiquitin-conjugating enzyme E2D 2 (UBE2D2), and heat shock 70kDa protein 9 (mortalin/HSPA9), encoding a glucose regulated 75 kilodalton protein previously reported as correlating with poor survival in colorectal cancer." (PMID 21297950, 2011).
influenza (2 papers, 2020 to 2023). An acute viral infection of the respiratory tract, occurring in isolated cases, in epidemics, or in pandemics; it is caused by serologically different strains of viruses (influenzaviruses) designated A, B, and C, has a 3-day incubation period, and usually lasts for 3 to 10 days. "UBE2D2 and RPS18 were reported to be stable in PBMCs collected 4 weeks after influenza vaccination." (PMID 36627346, 2023). "This study suggests the use of a combination of UBE2D2, RPS18, and ACTB for the study of influenza responses in PBMCs and T-cells, although ACTB alone may be the most optimal choice if choosing to compare target gene expression before and after viral stimulation." (PMID 32005148, 2020).
retinal degeneration (2 papers, 2024 to 2025). Degeneration of the retina. "Retinal degeneration caused by UBE2D/eff knockdown is rescued by human UBE2D2/4." (PMID 38168249, 2024). "We have found that human UBE2D2 can rescue retinal degeneration induced by eff RNAi in the context of polyglutamine disease, and that this results from the degradation of HMW Htt-polyQ." (PMID 38168249, 2024). "To this purpose, we expressed human UBE2B (homologous to Ubc6, DIOPT homology score = 13) and human UBE2D2 and UBE2D4 (homologous to eff, DIOPT scores of 13 and 10, respectively) and compared their capacity to rescue retinal degeneration compared to mock mcherry overexpression." (PMID 39879147, 2025). "On this basis, we expressed human UBE2B (homologous to Ubc6, DIOPT homology score=13) and human UBE2D2 and UBE2D4 (homologous to eff, DIOPT scores of 13 and 10, respectively) and compared their capacity to rescue retinal degeneration compared to mock mcherry overexpression." (PMID 38168249, 2024).
cerebral infarction (1 paper, 2020). An ischemic condition of the brain, producing a persistent focal neurological deficit in the area of distribution of the cerebral arteries. "We found that UBE2D2 is highly expressed in patients with AF complicated by cerebral infarction, compared with patients with AF alone." (PMID 32265825, 2020). "We speculate that in incidences of AF complicated by cerebral infarction, UBE2D2 may be involved by affecting the activity of ubiquitin protease and autophagy." (PMID 32265825, 2020). "Bioinformatics analysis can effectively identify the differential genes in patients with AF complicated by cerebral infarction vs. patients with AF alone, especially the MAPK1 and UBE2D2 genes." (PMID 32265825, 2020).
lymph node metastasis (1 paper, 2022). "Analysis of the clinical information table was performed, which clarified that circ-UBE2D2 was correlated with tumor node metastasis (TNM) staging and lymph node metastasis, and elevated circ-UBE2D2 predicted a poor prognosis (HR = 1.80; P < 0.05; 95% CI, 0.32–1.41)." (PMID 35196197, 2022).
lymphoma (1 paper, 2008). A malignant (clonal) proliferation of B- lymphocytes or T- lymphocytes which involves the lymph nodes, bone marrow and/or extranodal sites. "Genes whose expression was “high” in more than 95% of human lymphomas, whose gene names include: BZW2, H2AFY, SFRS3, NAP1L1, NOLA2, UBE2D2 and CCNG1 (p = 4.07×10−5)." (PMID 18535662, 2008).
melanoma (1 paper, 2021). A malignant, usually aggressive tumor composed of atypical, neoplastic melanocytes. "These are EGFR, ERRFI1, IL6, JAK2, PLXNC1, RGL3 which were found to be upregulated and CBL, CDC42, PIK3R3, STAT3, UBE2D2 and YWHAZ which were found to be downregulated; Melanoma has PLXNC1 as upregulated and TGFA as downregulated gene." (PMID 34764329, 2021).
pneumonia (1 paper, 2018). An acute, acute and chronic, or chronic inflammation focally or diffusely affecting the lung parenchyma, caused by an infection in one or both of the lungs (by bacteria, viruses, fungi, or mycoplasma.). "Simultaneously, based on target gene prediction and qRT-PCR analysis, we found that genes MYCBP2, UBE2V2, and UBE2D2 may play important roles in viral replication and Adv-induced pneumonia." (PMID 30405317, 2018).
Sepsis (1 paper, 2025). Sepsis is defined as life-threatening organ dysfunction caused by a dysregulated host response to infection. "The top five gene variables (MTF1, UBE2D2, DLAT, DLD, and ULK2) were selected as disease signature genes in the GLM model to construct a nomogram for predicting the incidence of sepsis-associated ALI." (PMID 38779731, 2025). "The expression of SLC31A1, CD274, ATOX1, MTF1, UBE2D1, DLD, and VEGFA was found to be upregulated, while that of DLST, UBE2D2, COX11, DLAT, GLS, FDX1, and ULK2 were significantly downregulated in patients with sepsis-associated ALI." (PMID 38779731, 2025).
Stroke (1 paper, 2020). Sudden impairment of blood flow to a part of the brain due to occlusion or rupture of an artery to the brain. "We thus suggest that UBE2D2 can be a potential diagnostic and therapeutic target for patients with AF complicated by stroke." (PMID 32265825, 2020). "UBE2D2 can also induce the detachment of intra-atrial thrombus by regulating the activity of ubiquitin enzyme and autophagy, thereby increasing the incidence of stroke." (PMID 32265825, 2020). "Therefore, we speculate that these highly expressed genes, most prominently MAPK1 and UBE2D2, are likely to be involved in incidences of AF complicated by stroke." (PMID 32265825, 2020).
viral infection (1 paper, 2018). "UBE2D2 is essential for the activation of MAVS and RIG-I in response to viral infection." (PMID 30405317, 2018).
tumor (9 papers, 2015 to 2024). "The LC cell lines with stable intervention of circ-UBE2D2, miR-376a-3p, and EIF4G2 expression are constructing to investigate the effects of circ-UBE2D2/miR-376a-3p/EIF4G2 axis on tumor growth in vivo." (PMID 35196197, 2022). "Therapeutically, intratumoral administration cholesterol-conjugated si-circ-UBE2D2 in a xenograft tumor model notably delayed tumor growth." (PMID 34400888, 2021). "However, when the concentration of copper at the tumor site is abnormal, copper can regulate autophagy through ULK1 and ULK2, and control protein quality through UBE2D2, which in turn affects the growth and progression of the tumor." (PMID 36891559, 2023). "Moreover, copper regulates autophagy through ULK1 and ULK2 and/or controls protein quality through UBE2D2, providing novel copper-dependent targets that can influence tumor growth and progression." (PMID 37600774, 2023). "Furthermore, copper provides new copper-dependent targets by regulating autophagy and/or controlling protein quality through UBE2D2, affecting tumor growth and progression." (PMID 37600774, 2023). "These two studies indicated that UBE2D3 expression is involved in cell cycle regulation via the degradation of cyclin D1; in consideration of this biological behavior, the present study proposes that UBE2D2 expression levels may promote tumor development." (PMID 25789002, 2015). "The difference analysis of 41 paired samples of TCGA-COAD showed that the mRNA levels of ARHGAP4, SIAH2, TRIM45, and WDR72 were significantly upregulated in the tumor group, while MID2 and UBE2D2 showed no statistical difference." (PMID 39268080, 2024).
cancer (4 papers, 2014 to 2024). A tumor composed of atypical neoplastic, often pleomorphic cells that invade other tissues. "UBE2D2 and NFKB2 may go through TLR4 to influence IRF1 to destroy the immune system and promote the occurrence and development of cancer." (PMID 34445498, 2021).
UBE2D2 also shares sentences with these, for which no sentence is quoted: Bladder cancer (2 papers); glioma (2); infection (2); non-small cell lung carcinoma (2); atrial fibrillation (1); endometrial cancer (1); lung carcinoma (1); Parkinson disease (1).